PDIA3 (protein disulfide isomerase family A member 3)
Diseases named in the same sentence as PDIA3 in open-access papers (continued):
Sharing a sentence is not in itself a finding about the gene and the disease.
tumor (continued). "Downregulation or loss of PDIA3 can lead to a deficiency in class I MHC expression, allowing tumor cells to evade recognition and destruction by cytotoxic T lymphocytes and other immune cells." (PMID 37909009, 2023). "This would be a key tool for further investigations of the roles of PDIA3 in tumor progression and metastasis." (PMID 36912485, 2023). "ERp57/PDIA3 is another potential factor modulating microglial pro-tumor polarization toward the M2 phenotype." (PMID 37012233, 2023). "The results indicated that PDIA3 was positively correlated with tumor-infiltrating CD8+ T cells (P = 5.26E-05) and macrophages (P = 2.56E-03), while it exhibited a negative correlation with tumor-infiltrating CD4+ T cells (P = 2.34E-03)." (PMID 37909009, 2023). "In this study, we introduced a novel biomarker, PDIA3, for EC and validated its expression using public datasets and primary tumor tissues." (PMID 37909009, 2023). "Since investigations to date have concentrated on whole tumor analyses by proteomics or transcriptomics, the cell types that express PDIA3 remain uncertain." (PMID 36374169, 2023). "Fernanda I Staquicini and colleagues discovered a cyclic peptide called CSSTRESAC that binds to a protein receptor called protein disulfide isomerase A3 (PDIA3), which is specifically expressed on the surface of M2-like tumor-associated macrophages (TAM)." (PMID 37601380, 2023). "PDIA3-specific T-cell clones were found to kill tumor cells through a Fas-FasL interaction, indicating their antitumor effector functions." (PMID 37909009, 2023). "Immunohistochemical analysis showed that patients with PDIA3 overexpression tended to have greater tumor differentiation, while patients with low expression of PDIA3 generally had poor differentiation in pathological tissues." (PMID 37909009, 2023). "Further analysis of paired tumor and normal tissues showed a consistent upregulation of PDIA3 in OSCC tissues." (PMID 38213579, 2023). "PDIA3 expression in tumor cells promotes microglia polarization toward the M2 phenotype and releases mediators such as CCL2 and COX-2 to activate the JAK/STAT pathway." (PMID 37700840, 2023). "PDIA3 showed moderate IHC staining in normal bladder, colon, esophagus, lung, prostate, and stomach tissues, but strong staining in tumor tissues." (PMID 36046686, 2022). "Further, Kaplan-Meier method was used to analyze the relationship between the methylation of PDIA3 promoter region and the prognosis of 33 tumor patients." (PMID 36046686, 2022). "PDIA3 acts as a robust tumor biomarker in influencing protein synthesis, degradation or secretion and then shaping the tumor microenvironment." (PMID 36429083, 2022). "Recently, a cyclic peptide was identified (CSSTRESAC) that specifically acts on ERp57/PDIA3, as 1α,25(OH)2D3 receptor, through vitamin D3 binding protein (DBP), present on the cell surface of tumor-associated macrophages (TAM)." (PMID 35109791, 2022). "On the contrary, PDIA3 showed moderate staining in normal thyroid tissues, but weak staining in tumor tissues." (PMID 36046686, 2022). "The high expression level of PDIA3 is an important potential biomarker for rapid tumor progression and poor prognosis." (PMID 36046686, 2022). "The ERp57/PDIA3 silencing seems to activate GB cells to produce IL24 (a tumor-suppressing protein) and leukemia inhibitory factor (LIF), inhibiting cell differentiation." (PMID 35109791, 2022). "The expression of PDIA3 in hepatocellular carcinoma is positively correlated with tumor grade and AFP level." (PMID 36046686, 2022). "Reducing protein disulfide isomerase family A member 3 (PDIA3) expression in GBM cells significantly limited the microglia pro-tumor polarization toward the M2 phenotype and the production of pro-inflammatory factors." (PMID 36429083, 2022). "The results showed that the expression level of PDIA3 (F = 2.74, PR (>F) = 0.0436) was significantly increased with the progression of tumor staging, and the difference was statistically significant." (PMID 36406049, 2022).
tumor (continued). "At the same time, the relationship between PDIA3 and tumor immune microenvironment was also discussed." (PMID 36046686, 2022). "PDIA3 showed weak staining in normal breast, kidney, liver, and uterus tissues, but moderate staining in tumor tissues." (PMID 36046686, 2022). "(B) Treatment of tumor-bearing mice with CSSTRESAC reduces the number of PDIA3-expressing TAM (F4/80+CD11b+IL-10highIL-12lowPDIA3+)." (PMID 34060472, 2021). "Several ER‐resident proteins (ERp29/PDIA9 and ERp57/PDIA3) were enriched up to ∼ 70% in the cytosolic fraction compared with only ∼ 10% enrichment in non‐tumor controls." (PMID 33710763, 2021). "In order to study the molecular mechanism of CALR involved in tumor progression, we used String and GeneMANIA databases finding that PDIA3, B2M, GANAB, CANX, and TAPBP interact with CALR." (PMID 34910788, 2021). "So far only one study has evaluated expression of PDIA3 in PCa tissue in which tumor samples with a higher Gleason score (GS 8–10) had higher expression of PDIA3 compared to GS 6 tumors." (PMID 33761087, 2021). "Future studies are necessary to investigate the mechanism about the tumor microenvironment and immunoregulatory role of PDIA3." (PMID 32687065, 2020). "Silencing of PDIA3 in GB cells resulted in reduced release by tumor cells of IL6 and COX2 and increased production of IL1β." (PMID 33153019, 2020). "Then, a specific analysis between PDIA3 and tumor microenvironment components showed that PDIA3 was positively associated with infiltrating immune and stromal cells, including DCs, MDSCs, TEM, Tregs, macrophages, mast cells, neutrophils, NK cells, monocytes." (PMID 32687065, 2020). "In the present study, we have evaluated both in GB cells and microglia the expression of PDIA3 in GB specimens collected from patients after surgical resection of the tumor." (PMID 33153019, 2020). "Due to the negative influence on antigen presentation and MHC PLC stability, downregulated MHC class I molecules facilitated tumor cells to avoid immune surveillance, which was also related to PDIA3 overexpression." (PMID 32687065, 2020). "Immunohistochemical analysis of tumor samples revealed ERp57/PDIA3 expression in GB cells as well as in GAMs." (PMID 33153019, 2020). "In the luminal phenotype tumour, PDIA3 was present in the epithelial glandular structures and was low or absent within the stroma." (PMID 33095243, 2020). "In GB cells, downregulation of ERp57/PDIA3 resulted in alterations of the pattern of cytokines secreted by tumor cells that affect the surrounding environment in their favor." (PMID 33153019, 2020). "Previous studies have shown that PDIA3 was found to contribute to the breakdown of immune surveillance, tumor cell invasion, and immunologic cell death." (PMID 32687065, 2020). "The results indicated that reduced PDIA3 expression/activity in GB cells significantly limited the microglia pro-tumor polarization towards the M2 phenotype and the production of pro-inflammatory factors." (PMID 33153019, 2020). "In fact, in the parenchyma, >50% of the cells were positive for PDIA3, while in the tumor, the percentage of cells expressing PDIA3 was about 40%." (PMID 33153019, 2020). "Unexpectedly, the tumor tissue presented a significantly lower percentage of PDIA3 stained cells in comparison with the surrounding parenchyma." (PMID 33153019, 2020). "By means of gene silencing or pharmacological inhibition using PUN, we demonstrated that PDIA3 is involved in the pro-tumor activity of GB cells and GAMs." (PMID 33153019, 2020). "In order to analyze the PDIA3 expression pattern in GB, we examined the tumor and surrounding parenchyma in tissue specimens collected after tumor surgical removal from 18 patients diagnosed with GB." (PMID 33153019, 2020). "In the basal-phenotype tumour, in which glandular structures are lost, PDIA3 appeared uniformly distributed." (PMID 33095243, 2020).
tumor (continued). "Immunohistochemistry analysis of TMA displayed that CALR and PDIA3 were mainly localized in the membrane and cytoplasm of the tumor cells." (PMID 29228584, 2017). "LC-MS/MS-based quantitative analysis showed that CALR and PDIA3 were significantly up-regulated in NSCLC tissues relative to adjacent non-tumor lung tissues." (PMID 29228584, 2017). "In conclusion, our results collectively provided a potential biomarker dataset for NSCLC prognosis and revealed that CALR and PDIA3 were over-expressed in NSCLC compared with adjacent non-tumor lung tissues." (PMID 29228584, 2017). "The selected dysregulated proteins CALR and PDIA3 were found to be over-expressed in NSCLC compared with adjacent non-tumor lung tissues." (PMID 29228584, 2017). "The over-expressions of CALR and PDIA3 in tumor tissues were confirmed by real-time PCR using 20 paired tissues, and verified by western blot analysis." (PMID 29228584, 2017). "In PDIA3 deficient mice, MHC I is impaired and negatively influences presentation of antigenic peptides helping tumours to escape from immune surveillance by cytotoxic T cells." (PMID 27566066, 2016). "Thus, tumor cells themselves express PDIA3, but further analyses with cell type-specific markers will be needed to determine its expression in tumor-associated cell types." (PMID 36374169, 2023). "The results revealed that PDIA3 acts as a robust tumor biomarker." (PMID 35401558, 2022). "Furthermore, immunofluorescence (IF) images showed that PDIA3 protein was mainly localized and distributed in the endoplasmic reticulum (ER) in A-431 and U251 tumor cell lines." (PMID 35401558, 2022). "Among those PDI proteins, PDIA3 mediates the induction of T cell tolerance, the differentiation of regulatory T cell, and the activation of macrophage/microglia, thereby contributing to the breakdown of immune surveillance and tumor cell invasion." (PMID 36003400, 2022). "In subcutaneous and orthotopic transplantation mouse tumour models, the STAT3 inhibitor napabucasin prevented tumour growth and induced the expression of calreticulin and the protein disulfide isomerase family A member 3 (PDIA3; also known as ERp57) but suppressed that of CD47 and GLUT1." (PMID 35665592, 2022). "Our proposed working hypothesis shows that the CSSTRESAC-DBP complex specifically binds to PDIA3 and elicits functional changes in PDIA3-expressing TAM within the tumor microenvironment." (PMID 34060472, 2021). "CALR together with PDIA3 has been shown to translocate from the ER to the cell surface, leading to the recognition of the tumor by dendritic cells and then to T cell mediated eradication of the tumor." (PMID 34830970, 2021). "The complex CSSTRESAC-DBP binds PDIA3 and eliminates PDIA3-expressing TAM from the tumor microenvironment (through an unknown mechanism), resulting in a pro-inflammatory local response and inhibition of tumor growth." (PMID 34060472, 2021). "Similarly, a reduced Kd would reflect a stronger binding between CCSTRESAC and PDIA3 with the consequent inhibition of tumor growth." (PMID 34060472, 2021). "In particular, we investigated the PDIA3 expression in the tumor and the nearby parenchyma from 18 GB patients and our data showed the expression of PDIA3 not only in tumor cells but also in GAMs, supporting its potential role in cellular and molecular processes related to GB." (PMID 33153019, 2020). "Then we also quantified the intra-tumor expression of PDIA3." (PMID 32687065, 2020). "Therefore, since microglia represent the main cell type that infiltrates the tumor we analyzed the expression of PDIA3 in GAMs." (PMID 33153019, 2020). "Additionally, PDIA3 was also involved in suppression of anti-tumor immunity via multiple immune regulatory processes." (PMID 32687065, 2020). "In addition, PDIA3 expression was correlated with poor differentiation and large tumor size in the AC subtype." (PMID 23782473, 2013).
tumor (continued). "Therefore, the expression of PDIA3 and its role in tumor progression seems to be tumor type specific." (PMID 23782473, 2013). "In this study, we determined the expression levels of CCT2 and PDIA3 by immunohistochemistry staining in tumor samples from 46 SC/ASC and 80 AC patients, and then investigated the relationship between these expression levels and tumor progression as well as the prognosis." (PMID 23782473, 2013). "Therefore, the high level of PDIA3 expression is an important potential biomarker for rapid tumor progression and poor prognosis." (PMID 23782473, 2013). "Interestingly, expression levels of PDIA3 in Gleason pattern 3 (CA3) seem to depend on the accompanying Gleason pattern in the tumor." (PMID 20035634, 2009). "Considering that PD-L1, sporting the guise of immune cell membranes, coalesces with PD-1 to curtail the activation and cytotoxic prowess of the same towards neoplastic cells, a surge in PDIA3 could champion the veiling of tumor entities from immune surveillance." (PMID 38761176, 2024). "Cox proportional risk regression model showed that PDIA3 expression in ACC (P = 0.011), CESC (P = 0.006), GBM (P = 0.003), HNSC (P = 0.004), KICH (P = 0.003), KIRP (P = 0.001), LAML (P = 0.022), LGG (P < 0.001), UCEC (P = 0.05), and UVM (P = 0.002) was associated with OS of tumor patients." (PMID 36046686, 2022). "The reduced PDIA3 expression/activity in GB cells significantly limited the microglia pro-tumor polarization towards the M2 phenotype and the production of pro-inflammatory factors, supporting a role of PDIA3 expression in GB-mediated pro-tumor activation of microglia." (PMID 35109791, 2022). "Protein disulfide isomerase A3 (PDIA3) is a kind of thiol oxidoreductase with a wide range of functions, and its expression is elevated in a variety of tumors, which is closely related to the invasion and metastasis of tumor cells, and has a significant impact on the immunogenicity of tumor cells." (PMID 36046686, 2022). "Therefore, all these data suggest that a partial blockade of PDIA3 in T98G cells might attenuate the pro-tumor microglia activation since it tends to reduce the M2 parameters (urea and ARG1) and IL6 release by microglia." (PMID 33153019, 2020). "Some studies show that CALR and PDIA3 can translocate from the ER to the cell surface and facilitate tumor cell recognition and engulfment by dendritic cells and subsequent T-cell mediates elimination of the tumor, inducing the activation of adaptive immune responses in the tumor microenvironment." (PMID 29228584, 2017). "Thus, the upregulation of PDIA3 may relevant to tumor formation and contribute to REV-A replication." (PMID 28097424, 2017). "Cumulative data suggest the possible applicability of inhibition of PDIA3 activity to modulate ECM composition and functionality within the tumor microenvironment." (PMID 36912485, 2023). "After gene silencing or specific inhibition of ERp57/PDIA3 by punicalagin, the authors demonstrated that ERp57/PDIA3 is involved in the pro-tumor activity of GB cells and GAMs." (PMID 35109791, 2022). "TMTC3 acts as a binding partner for protein disulfide isomerase family A member 3 (PDIA3) and this gene’s expression plays a role in GBM-mediated pro-tumor activation of microglia." (PMID 35877430, 2022). "The corresponding heat map further proved that HSP90B1 was positively correlated with the six genes (HSPA5, PDIA3, MANF, PDIA4, CALR, and PDIA6) in various tumours." (PMID 36291587, 2022). "As shown in the volcano plot, SU decreased GZMB expression and upregulated genes related to inflammatory activation (FOS, JUN, NFKBIA, DUSP2, JAK1, PIM1), tumor immunity (CD47, PCBP2, EIF5A, PDIA3, EGR1), and DNA damage (H2AFX, DDIT3, GADD45B)." (PMID 34824394, 2021). "(C-D) PDIA3 expression in TAM and co-localization with the pan-macrophage marker CD68 as detected by immunofluorescence of tumor tissue sections from tumor-bearing mice administered iv with anti-PDIA3 antibody (C) or CSSTRESAC-phage (D)." (PMID 34060472, 2021).
tumor (continued). "The top genes in cold tumor are ARF1, PDIA3, ALDOA, FKBP2, NDUFS5, NDUFC1, COX7A2, C14orf2, LNX1, and BTBD6." (PMID 33816503, 2021). "By double staining for PDIA3 and IBA1 (a macrophage-microglia marker), we found that the percentage of microglia macrophages expressing PDIA3 present in the tumor was significantly higher than that in the parenchyma." (PMID 33153019, 2020). "Thus, PDIA3-silenced GB cells may continue to attract microglia/macrophages in the tumor microenvironment but tend to activate a different phenotype that might be speculated as tumor resolving." (PMID 33153019, 2020). "In fact, taking into account only the microglia-macrophage cell population, in the tumor, 15% of the IBA1 positive cells also expressed PDIA3, whereas in the parenchyma, the percentage of double positive cells was 10%." (PMID 33153019, 2020). "In high PDIA3 expression samples, frequently amplified genomic peaks were detected in oncogenic drivers, including PDGFRA, EGFR and CDK4; in addition, tumor suppressor genes, such as CDKN2A/CDKN2B and PTEN were observed a deletion peak." (PMID 32687065, 2020). "Tumour cell interactions with fibroblasts have important roles in driving tumour progression and PDIA1 and PDIA3 have known substrates that are destined for secretion." (PMID 33095243, 2020). "On the other hand, pS727-STAT3 and the glutathionylated-STAT3 forms were highly expressed in the most malignant tumor (Gleason 8 and 9) together with an increase in the APE1/Ref-1 and PDIA3/ERp57 levels which are known to be present under oxidative stress." (PMID 28489571, 2017). "In contrast to the expression of PDIA3 in SC/ASC, we found that the expression of PDIA3 in AC significantly correlated not only with large tumor size, higher TNM stage, and lymph node metastasis, but also with poor differentiation (P < 0.05)." (PMID 23782473, 2013). "Western blotting was used to quantify the expression of PGAM-1, HSPD1, PDIA3 and SSP411 (which were all upregulated in bile from CC patients) in eight pairs of CC and adjacent non-tumor bile duct tissues." (PMID 23118872, 2012). "Immunohistochemical analysis was performed to characterize the distribution of PGAM-1, HSPD1, PDIA3 and SSP411 in surgical tumor tissues." (PMID 23118872, 2012). "Because 1,25-(OH)2D3 may compete out the effects of CSSTRESAC, binding to PDIA3-expressing TAM in the presence of 1,25-(OH)2D3 may be abrogated, and tumor cells can continue to grow." (PMID 34060472, 2021). "PDIA3 was proven to participate in regulating proliferation, invasion, and migration in many tumors—for instance, PDIA3 in GBM regulates macrophage/microglia pro-tumor activation." (PMID 34950658, 2021). "Moreover, in some subsets including CD8 TEM, SU increased the level of tumor immunity-related genes, including CD47, PCBP2, EIF5A, and PDIA3." (PMID 34824394, 2021). "Moreover, PDIA3 was found to positively correlate with ESTIMATE scores and diverse infiltrating immune and stromal cell types localizing in tumor microenvironment." (PMID 32687065, 2020). "Further studies will be needed to identify the secreted proteins that differ between WT and Pdia3−/− MEF, which might include ECM proteins or chemokines that have known roles in tumour progression." (PMID 33095243, 2020). "FatiGO+ analysis showed that tumor libraries had significantly more expressed genes related to "cell organization and biogenesis" (GO:0016043), KRT7, PDIA3, PPGB and TRAPPC5 (p = 0.005); and "ligase activity" (GO:0016874), UBE2S and MTHFD1 (p = 0.028) than normal libraries." (PMID 18302799, 2008). "Considering the role of PDIA3 in the assembly of the MHC class I antigen processing complex, these findings suggest that down-regulation of PDIA3 may contribute to more aggressive tumor behavior." (PMID 37909009, 2023). "Thus, PDIA3 activity appears important for assembly of protein-protein networks that function to structure the ECM and in communications between normal and tumor cells that support tumor progression." (PMID 36374169, 2023).